NPM1P7 (nucleophosmin 1 pseudogene 7)
Synonyms: NG7-6; formerly NPMP7; NPM1P16
Gene: Processed pseudogene on chromosome 12 (9,695,384 to 9,696,227, forward strand). Ensembl gene ENSG00000213443.
Diseases named in the same sentence as NPM1P7 in open-access papers:
NPM1P7 is named in the same sentence as 1 disease in open-access papers, as found by Europe PMC text mining. Sharing a sentence is not in itself a finding about the gene and the disease.
NPM1P7 shares sentences with these, for which no sentence is quoted: hepatocellular carcinoma (1 paper).